IL4 (interleukin 4)
Diseases named in the same sentence as IL4 in open-access papers (continued):
Sharing a sentence is not in itself a finding about the gene and the disease.
malaria (continued). "Our findings add to the understanding of the cytokine pathways involved in control and recovery from various infections, especially during coinfection, and suggest a prominent role for cytokines, such as IL-4, that have historically received less attention in human malaria." (PMID 27418744, 2016). "Moreover, the recurrent malaria group displayed significantly augmented levels of IL-10, IL-6, and IL-4 as compared to patients with primary malaria (p < 0.0005, p < 0.005 and p < 0.05, respectively)." (PMID 27581163, 2016). "In this study, levels of the IL-10, IL-6 and IL-4 were higher in patients with recurrent malaria." (PMID 27581163, 2016). "Furthermore, HB and HT had several negative interactions with inflammatory mediators (IL-17, IL-12, IL-5, IL-4) in the malaria group." (PMID 26271921, 2015). "As such, the presence of the TA haplotype could be altering the gene-gene interactions of IL-13 and IL-13Rα1, thereby promoting enhanced IL-4 production leading to inhibition of erythropoiesis in children with malaria." (PMID 23521898, 2013). "In contrast, exacerbated Th2 responses may be detrimental in malaria because IL-4, secreted by Th2 cells, suppresses Th1 differentiation and macrophage activation and drives the synthesis of non-opsonizing antibodies including IgE." (PMID 23358441, 2013). "Children also presented significantly higher IL-4 levels compared to malaria-exposed adults." (PMID 23437061, 2013). "Individuals with asymptomatic malaria displayed multiple significant interactions involving IL-4." (PMID 23433077, 2013). "HBB, IL4, IL12, TNF, LTA, NCR3 and FCGR2A polymorphisms have been associated with malaria resistance in humans, whereas cytophilic immunoglobulin G (IgG) antibodies are thought to play a critical role in immune protection against asexual blood stages of the parasite." (PMID 22947458, 2012). "Furthermore, HBB, IL4, TNF, and FCGR2A have been associated with both malaria resistance and IgG levels." (PMID 22947458, 2012). "According to previous findings, the IL4-590 C/T polymorphism influences the balance between IL4 and IFN-γ and thus, could alter the severity of malaria." (PMID 20003246, 2009). "The present study did not reveal any association between IL4-590 C/T transition and the severity of malaria in either with or without previous malaria experiences, although there was an association between IL4-590 TT genotype and the levels of anti-P." (PMID 20003246, 2009). "Allele and genotype frequencies of IL4-590 polymorphism in complicated and uncomplicated malaria patients with or without previous malaria experiences." (PMID 20003246, 2009). "Moreover, an ethnic group in West Africa, the Fulani, shows a functional deficit in Treg related gene expression, as well as elevated levels of peripheral blood malaria-specific Th1 (IFNγ) and Th2 (IL-4) producing cells." (PMID 19680449, 2009). "Our data revealed that infected baso IL-4/IL-13 (−) mice exhibited increased ileal mastocytosis, intestinal permeability, and bacteremia relative to infected controls, suggesting that basophil-derived IL-4 and IL-13 blunt MC-dependent intestinal permeability and bacteremia in malaria." (PMID 38780542, 2024). "Befitting any general immune response mechanism, various cytokines may potentially modulate ICAM1 expression, of which we have found evidence for statistical association of IL1, IL4 (and its receptor, IL4R), IL6, IL13, TLR2, TLR4, and IFNG (and its receptor, IFNGR1) polymorphisms with malaria." (PMID 37287037, 2023). "In addition, IL-4 levels between uncomplicated malaria and healthy controls were comparable, but several sources of heterogeneity, such as study designs, continents, age groups, and types of blood samples for IL-4 measurement, were needed for consideration before interpreting the results." (PMID 35820892, 2022). "Therefore, from the meta-analysis results, it might be possible that IL-4 levels between severe and uncomplicated malaria were comparable." (PMID 35820892, 2022).
malaria (continued). "Additionally, other studies investigated IL-4 concentrations in patients with severe malaria." (PMID 35820892, 2022). "Therefore, these confluent events from responses to both pathogens (increased production of IL-10, CCL2 protective role in malaria, as well as combined effects of IL-4 and IL-10) could enable the host to respond properly without unbalanced inflammation." (PMID 31233500, 2019). "Indeed, in future studies it would be preferable to explore other immune responses induced by these PSNPs vaccines in the context of blood-stage malaria, including investigating other cytokines (i.e., TNF, IL-5, IL-17) in addition to the hallmark Th1 and Th2 cytokines IFN-γ and IL-4, respectively." (PMID 30930890, 2019). "Circulating concentrations of IL-4, IL-5, and IL-7 differed across the groups (P < 0.001 for all) and were significantly elevated in the G[+] and G[−] coinfected children, relative to both children with malaria-only (P < 0.001 for all) and healthy controls (P ≤ 0.024 for all), respectively." (PMID 27418744, 2016). "In the context of our study, independently of any morbidity linked to malaria, no biological or immunological advantage could be deduced for the newborns from the IL-4 genetic characteristics of their respective mothers." (PMID 23668806, 2013). "Indeed, IL-4 is expressed at lower levels in malaria infected WSX-1−/− mice than in WT mice." (PMID 23593003, 2013). "In this study, we aim to investigate the contribution of three functional IL-4 polymorphisms rs2243250 (-590 C>T, promoter), rs2070874 (-34 C>T, 5′UTR) and rs79071878 (intron-3, 70 bp VNTR) with P. falciparum malaria infection in well-defined malaria cases and in ethnically matched controls." (PMID 23110190, 2012). "It has been also shown that cytokines play an important role in the immunopathology of malaria and many field studies have described an association of specific cytokines with severity of disease, in particular IL-2, IL-12, IFN-γ, IL-1β, IL-6, TNF, IL-4, IL-10, MIP-1β, and TGF-β." (PMID 22280502, 2012). "It is also interesting to note that another member of STAT family (i.e. STAT6) could be involved in mediating erythropoietic suppression during acute blood-stage malaria and that interleukin-4 (in 5q31–q33 region) and possibly interferon-γ could also play a role in this mechanism." (PMID 20657648, 2010). "In the present study, fine association mapping for a cytokine gene cluster including IL4, IL5, and IL13 on chromosome 5q31 was conducted using the same malaria subjects to refine the region containing a primary variant or a haplotype susceptible to severe malaria." (PMID 19840389, 2009). "In contrast, no such associations could be found when the IL4-590 genotypes were compared between complicated malaria patients without previous malaria experiences (CMN) and uncomplicated malaria patients." (PMID 20003246, 2009). "We observed increased IL-4, CXCL1, CXCL2, and CCL4 within the placenta, which have all been reported to be increased in humans, mice, or in vitro models of malaria (49, –, 52)." (PMID 40470930, 2025). "In humans, malaria during pregnancy results in elevated levels of numerous cytokines, including IFN-γ, TNF-α, IL-4, IL-6, IL-10, and CXCL9 in peripheral circulation, with some of these cytokines linked to increased risk of pregnancy loss." (PMID 40470930, 2025). "Distinct cytokine profiles in malaria and HBV coinfections were TNF, IFN-γ, IL-4, IL-6, IL-10, IL-12, and CCL2." (PMID 36716305, 2023). "TNF and IL-4 levels were significantly decreased in malaria and HIV coinfections compared to malaria monoinfections." (PMID 36716305, 2023). "Malaria and dengue coinfections showed a significant increase in proinflammatory cytokines such as IFN-γ, IL-1, IL-6, and IL-12; Th2 cytokines such as IL-4; anti-inflammatory cytokines such as IL-10 and IL-13; and Th17 cytokines such as IL-17." (PMID 36716305, 2023).
malaria (continued). "Malaria coinfections with bacteremia were characterized by distinct cytokine profiles, including elevated IFN-γ, IFN-α, IL-4, IL-7, IL-12, IL-15, and IL-17 levels and decreased TNF levels, indicating a strong cytokine response." (PMID 36716305, 2023). "For malaria and virus coinfections, increased TNF, IFN-γ, IL-6, and CCL4 levels and decreased IL-4, IL-7, IL-12, TGF-β, and CCL3 levels were observed in malaria coinfections compared to dengue monoinfection." (PMID 36716305, 2023). "Distinct cytokine profiles in malaria and schistosomiasis coinfections were TNF, IFN-γ, IL-4, IL-5, IL-10, TGF-β, and CXCL8." (PMID 36716305, 2023). "For intestinal parasite infections, increased TNF, IL-1, IL-6, IL-10, CCL2 and decreased IL-4, IL-17, TGF-β were observed in malaria coinfections compared to intestinal parasite monoinfection." (PMID 36716305, 2023). "Distinct cytokine profiles in malaria and intestinal parasite coinfections were TNF, IL-2, IL-4, IL-6, and IL-10." (PMID 36716305, 2023). "Distinct cytokine profiles in malaria and HIV coinfections compared to malaria monoinfections were increased IL-12, CXCL9, CXCL11, IL-18, and G-CSF levels and decreased TNF and IL-4 levels." (PMID 36716305, 2023). "Increased IFN-γ, IL-4, IL-10, IL-27, CXCL10, and CX3CL1 levels were observed in malaria monoinfection compared to HIV virus monoinfection." (PMID 36716305, 2023). "Most of the cytokines that were investigated in malaria and other parasite coinfections were TNF, IFN-γ, IL-2, IL-4, IL-6, and IL-10." (PMID 36716305, 2023). "We have found that many of the cytokines involved in malaria (TNF-α, IFN-γ, IL-4, and IL-10) play a double role, as a friend or as an enemy." (PMID 34790829, 2021). "CXCL9 and IL-4 were the top markers when we analyzed asymptomatic malaria vs. controls, whereas IL-6 and CXCL10 were highlighted when symptomatic vs. asymptomatic malaria patients were compared." (PMID 34727121, 2021). "While children with asymptomatic malaria have increased IFNγ, TNF and IL-4 levels, IL-10 and CXCL10 were elevated in asymptomatically infected pregnant women." (PMID 33407502, 2021). "Children with either microscopic or submicroscopic asymptomatic malaria exhibited higher levels of IFN-γ, IL-17A, and IL-4 compared to uninfected controls." (PMID 33281757, 2020). "Similar results were shown in our recent study with MSP4/5 (blood stage malaria antigen) conjugated NPs where PS NPs-MSP4/5 induced higher IFN-γ T-cell responses and comparable IL-4 T-cell responses compared to MSP4/5 immunized with alum." (PMID 32485944, 2020). "For children with microscopic asymptomatic malaria, IL-6 was found to positively correlate with TNF-α (r = 0.59, p < 0.0001), IL-4 (r = 0.39, p = 0.017), and IL-10 (r = 0.50, p = 0.002)." (PMID 33281757, 2020). "Patients with malaria-HBV coinfection presented elevated concentrations of multiple variables such as IFN-γ, TNF-α, IL-4, IL-10, CCL2, and reduced levels of IL-12 and creatinine levels when compared to those with asymptomatic vivax malaria monoinfection." (PMID 31233500, 2019). "This augmented production of IL-10 alongside IL-4 heightened levels can directly downregulate key proinflammatory cytokines such as TNF-α, and thus have a protective effect against severe malaria presentations." (PMID 31233500, 2019). "Since TGF-b and IL-4 are the main cytokines that induce AID expression, their expression levels in Th cells of malaria patients were analysed." (PMID 30373593, 2018). "Since the reduction of malaria parasite burden in the liver in co-infected mice was reversed in IFN-γ-/- and IL-4-/- mice, we assume that the mechanism of protection is both IFN-γ and IL-4 dependent." (PMID 29373600, 2018). "Next, to investigate the profile of the infectious process triggered by P. vivax in patients diagnosed with malaria, patients were divided into two groups using serum TNF-α and IL-4 levels to focus on the serum cytokine profile." (PMID 30126413, 2018).
malaria (continued). "While much of the protective immune response to malaria is thought to be due to liver tissue-resident CD8 T cells, IL-4-secreting CD4+ T cells are thought to be critical for mediating CD8 T cell response to malaria liver antigens." (PMID 29449839, 2017). "Circulating levels of interferon (IFN)-γ, interleukin (IL)-2, IL-4, IL-6, IL-10, IL-12p70, IL-13, IL-17A and tumor necrosis factor (TNF) were assessed in sera of patients infected with active VL and/or malaria and healthy individuals from Gedarif State, Sudan." (PMID 24886212, 2014). "After evaluating the cytokine profile (IL-2, IL-4, IL-6, IL-10, TNF-α, IFN-γ and IL-17) in the patients’ sera, levels of IL-6, IL-10 and IFN-γ were elevated in malaria patients compared to HV." (PMID 23723981, 2013). "Children also had higher IL-12 (P = 0.0001), IL-4 (P = 0.003), IL-1β (P = 0.024) and TNF (P = 0.006) levels compared to malaria-exposed adults." (PMID 23437061, 2013). "In the group of individuals who survived severe malaria, TNF, IL-4 and direct bilirubin seemed to have a distinguished pattern of connections, albeit, no clear clusters were evident and there was overall low connectivity between the markers studied." (PMID 23433077, 2013). "Blood cells from donors in malaria endemic areas stimulated with Plasmodium antigens are known to activate many types of cells, with production of both IFN-γ (Th1 type) and IL-4 (Th2 type)." (PMID 22280502, 2012). "It has also been suggested that anti-inflammatory Th2-type cytokines (IL-4, IL-10, and TGF-beta) downregulate Th1-type cytokines and the proinflammatory response, thereby preventing subjects from severe forms of malaria." (PMID 23316245, 2012). "A significant inverse correlation between IL-4 to INF-γ ratio and peripheral parasitaemia in malaria patients has been documented." (PMID 23110190, 2012). "With regards to Th2 cytokines, while it has been demonstrated that an antibody defence to malaria can be mounted in the absence of IL-4, IL-4 production does play a role in upregulation of the humoral immune response to malaria." (PMID 40520249, 2025). "IL-4 is a potent immunomodulatory cytokine that correlates with the severity of malaria hyperparasitaemia but not the severity of the disease." (PMID 36716305, 2023). "An analysis of the cord blood revealed that TNF, IL-1β, and IL-5 were associated with severe malaria but IL-4, IL-6, IFN-γ, and IL-10 did not relate to severe malaria." (PMID 36668942, 2023). "Distinct cytokine profiles in malaria and CHIKV coinfections were IFN-γ, IL-4, IL-12, and IL-13." (PMID 36716305, 2023). "Three studies reported lower IL-4 levels in cerebral malaria than in noncerebral severe malaria (50%)." (PMID 35820892, 2022). "Based on the limited number of studies included in the meta-analysis, consideration of IL-4 as an alternative prognostic factor for malaria severity is not warranted until additional investigations have been conducted." (PMID 35820892, 2022). "The difference in IL-4 levels between cerebral and noncerebral severe malaria was reported in six studies." (PMID 35820892, 2022). "The secondary outcome measure was the difference in IL-4 levels between patients with severe cerebral malaria and patients with noncerebral severe malaria." (PMID 35820892, 2022). "Based on the limited number of studies included in the meta-analysis, until additional investigations have been conducted, IL-4 consideration as an alternative prognostic factor for malaria severity is not warranted." (PMID 35820892, 2022). "The meta-regression results showed that the regression coefficients, including study designs, types of severe complications, malaria parasitaemia, and method for IL-4 measurement, were not zero (P < 0.05)." (PMID 35820892, 2022). "The difference in IL-4 levels between cerebral malaria (96 cases) and noncerebral severe malaria (108 cases) was estimated using the data from four studies that reported quantitative data (mean and SD, or median and range) of IL-4 levels." (PMID 35820892, 2022).
malaria (continued). "Conversely, the present results were different from the previous findings in an area with unusable malaria transmission in Sudan, where higher levels of IL-4 and IL-10 in the non-infected group was reported." (PMID 33422078, 2021). "The subgroup IL-15, IL-17 and IL-4 was negatively correlated to the cohort containing IL-6, IL-1Ra MIP-1β, IL-7 and IP-10, which, interestingly, has been shown to be a marker for different infections including malaria and dengue fever." (PMID 34299123, 2021). "Elevated levels of IL-4 and IL-10 and reduced levels of IL-6 were detected in the malaria positive samples in comparison to the negative ones in the three types of the samples investigated." (PMID 33422078, 2021). "In addition, both coinfected groups had increased IL-4, IL-5, IL-7, IL-12, IL-15, IL-17, IFN-γ, and IFN-α and decreased TNF-α relative to malaria alone." (PMID 27418744, 2016). "The group of malaria mono-infected patients exhibited a biosignature composed by higher levels of IL-10 and CCL2 whereas the group of dengue mono-infected individuals displayed a signature with high expression of IL-4, IL-7 and Il-12 in plasma." (PMID 26271921, 2015). "Two children induced DBLα-tag specific IgG4 responses after the acute malaria episode but neither child had induced IL-4–secreting CD4+ T cells." (PMID 24453249, 2014). "Clinical malaria cases exhibited an immunological profile qualitatively similar to that of the VL patients, with increased concentrations of TNF, IL-6 and IL-10 (P <0.0001) and, to a less extent, IFN-γ and IL-17A (P <0.01), IL-4 and IL-12p70 (P <0.05)." (PMID 24886212, 2014). "The potential anti-inflammatory effect of IL-4 in the immune response during malaria is not yet fully understood." (PMID 23433077, 2013). "Support for this modulatory hypothesis comes from the description that IL-10 and IL-4 can directly down regulate pro-inflammatory cytokines such as IL-6, TNF and IL-1β and prevent severe forms of malaria." (PMID 23433077, 2013). "It has been reported that the carriers of TT with cerebral malaria had elevated total IgE compared to non-carriers and suggested that the IL-4 play a regulatory role in the pathogenesis of malaria in Ghanaian children." (PMID 23110190, 2012). "We did not see marked differences in Th2 cytokines (e.g., IL-4, IL-10) which have been shown to be produced by inducible Tregs and limit malaria pathogenicity." (PMID 22348117, 2012). "Several studies suggest that the balance between pro- (TNF-α, IFN-γ, IL-8) and anti-inflammatory (IL4, IL-10, TGF-β) cytokines determines the degree of malaria parasitaemia, the level of anaemia, the clinical severity, the presentation, and/or the outcome of infection." (PMID 21867552, 2011). "falciparum IgG1 and IgG3 levels (median) according to IL4-590 genotypes in complicated malaria patients with or without previous malaria experiences." (PMID 20003246, 2009). "The role of IL-4 in human malaria has not been extensively studied." (PMID 38404582, 2024). "For the Molecular function category screened genes were correlated with interleukin 4 and 8 receptor binding followed by toxic substance binding, Finally, the KEGG pathway for the selected protein coding genes were found to be involved in inflammatory bowel disease, Malaria and Legionellosis." (PMID 37648727, 2023). "IL-4 levels in patients with cerebral and noncerebral severe malaria were reported in six studies." (PMID 35820892, 2022). "However, for the malaria group, four distinct correlation patterns were observed; first pattern (CCL4, CCL2, CCL3, IL12 and IL2), second pattern (IL-17A, IL-1β, CCL11, IL4), third pattern (IL5, IL7, IL13), and fourth pattern (IL1RA, CXCL10, TNFα, IL2R, CXCL9, IL6)." (PMID 35811678, 2022). "This study showed higher mean IL-4 levels in severe rather than uncomplicated malaria." (PMID 35820892, 2022).